ICOS (inducible T cell costimulator)
Diseases named in the same sentence as ICOS in open-access papers (continued):
Sharing a sentence is not in itself a finding about the gene and the disease.
Arthritis (8 papers, 2008 to 2025). Inflammation of a joint. "ICOS has been shown to be indispensable in collagen-induced and K/BxN arthritis models, and certain ICOS polymorphisms are associated with RA." (PMID 24605340, 2014). "Moreover, the arthritis scores of CIA mice were indicated to be more associated with the population of CD19+ICOSL+ B cells when compared with CD4+ICOS+ T cells (r = 0.4657, P = 0.0025 vs r = 0.3720, P = 0.0181)." (PMID 36405702, 2022). "ICOS signalling was shown to be required for collagen induced arthritis, and ICOS-ICOSL blockade targeting ICOSL significantly ameliorated joint inflammation, disease progression and severity." (PMID 38077329, 2023). "In this sense, we observed a higher proportion of CXCR5+ T cells in the lymph nodes of p110α−/−ΔT in the pre-arthritis stage and an increased expression of the surface markers ICOS, CXCR5 and CD44 in T-cell blasts of p110α−/−ΔT mice." (PMID 34203838, 2021). "Blockade of either ICOS or CD154 interaction with their respective ligands is protective in murine models of arthritis and suppresses autoantibody production." (PMID 20053277, 2010). "This is a relevant finding, because we observed an association of ICOS expression on Treg with PsA disease activity as measured by PASDAS (range 0–10), which takes arthritis, enthesitis, dactylitis, C-reactive protein, physician disease activity score and two PROs into account." (PMID 36450783, 2022). "To determine the effect of co-stimulatory molecules in established arthritis, we conducted the same in vitro experiments by using CTLA-4Ig, anti-ICOS, and anti-CD40L mAbs." (PMID 18534002, 2008). "ICOS-dependent PI3K signaling controls the induction and maintenance of collagen-induced arthritis in the mouse, and ICOS knockout mice on the DBA/1 background are completely resistant to collagen-induced arthritis and show no inflammation in the joints." (PMID 34203838, 2021). "Monoclonal antibodies to TNF-α, IFN-γ, IL-12, CD40L, inducible co-stimulator (ICOS), and cytotoxic T-lymphocyte antigen 4 immunoglobulin (CTLA-4Ig) were used to block TNF-α and IFN-γ production, examine clinical index in mice with GPI-induced arthritis, and determine anti-GPI antibody production." (PMID 18534002, 2008).
atherosclerosis (8 papers, 2013 to 2024). A disease characterized by the build-up of fatty material and calcium deposition in the arterial wall resulting in partial or complete occlusion of the arterial lumen. "Hematopoietic deficiency in ICOS or PD-1—inhibitory receptors of the TNF superfamily expressed by T cells—reduces Treg suppressive functions and survival and enhances atherosclerosis." (PMID 33805071, 2021). "In the present study we attempted to investigate the direct effect of the IL25-induced splenic ILC2 (Lin−CD45+IL17RB+ICOS+IL7raint) population on the development of atherosclerosis by its adoptive transfer to hypercholesterolaemic apoE−/− mice." (PMID 31823769, 2019). "In the present study we attempt to further characterize the splenic IL25-induced ILC2 subset (Lin−CD45+IL17RB+ICOS+IL7raintermediate) as well as investigate the cells subset’s direct effect on atherosclerosis development through its adoptive transfer to atherosclerosis-prone apoE−/− mice." (PMID 31823769, 2019). "ICOS also has been found to function in vascular diseases such as atherosclerosis." (PMID 24079748, 2013).
sarcoidosis (8 papers, 2019 to 2024). Sarcoidosis is a multisystemic disorder of unknown cause characterized by the formation of immune granulomas in involved organs. "Moreover, Sakthivel and colleagues reported high expression levels of ICOS in lung Tregs of pulmonary sarcoidosis patients, and it was particularly high in patients with Lofgren’s syndrome (LS) compared with NLS, thus associating the degree of ICOS expression on Tregs with prognosis of sarcoidosis." (PMID 32983168, 2020). "(d) In addition to LIGHT, sarcoidosis-associated ILC1s also expressed high levels of CD40L, BAFF, and ICOS, which are well-established B cell–activating cytokines." (PMID 39225100, 2024). "Sarcoidosis-activated ILC1s express CD40L, ICOS, and BAFF, which were previously shown to mediate direct interactions between ILCs and B cells." (PMID 39225100, 2024). "Advanced stage sarcoidosis is characterized by anergic CD4+ T lymphocytes expressing low levels of NF-ATc2 which is necessary for CD40L and ICOS expression." (PMID 33036432, 2020). "Specifically, early T effector cells (ETE) from sarcoidosis patients had significant downregulation of TCR signaling (labeled “SLE T cell signaling pathway” here) and ICOS-ICOSL signaling, as well as PI3K/AKT, ERK/MAPK, NFAT, ERBB2 (TOB), sirtuin, and mTOR signaling, relative to controls." (PMID 33363531, 2020). "Additionally, Löfgren’s syndrome patients exhibited Treg expressing higher levels of Inducible Co-Stimulator (ICOS) compared to non-Löfgren’s syndrome sarcoidosis." (PMID 33036432, 2020). "If lacking CD40L and ICOS-mediated signaling, B cells could become anergic/dysfunctional and lose the ability to undergo isotype switching, which may explain the deficit of memory class-switched B cells observed in sarcoidosis." (PMID 33036432, 2020). "Furthermore, no labeling of ICOS, CD35, or MECA79 in the sections of four sarcoidosis samples studied was registered." (PMID 38385142, 2023).
viral infection (8 papers, 2016 to 2025). "Using ICOS-deficient mice, we show here a role of ICOS in the homeostasis, development and function of NK cells with consequences to NK-dependent responses against in vivo viral infection." (PMID 31283790, 2019). "Importantly, salivary gland IL-10+ T cells expressed high levels of the co-stimulatory molecule ICOS that has previously been implicated in the development of IL-10-secreting CD4+ T cells during viral infection." (PMID 27926930, 2016). "Here, we found that Runx1 overexpression represses GC Tfh differentiation during viral infection, which is likely via repression of ICOS expression in early Tfh and Th1 cells." (PMID 39677644, 2025). "Accordingly, we have used ICOS-KO mice to assess the importance of ICOS in NK cell homeostasis and differentiation, and in the response to virus infection in vivo." (PMID 31283790, 2019). "Of interest, ICOS- and ICOSL-deficient patients have been associated with combined T- and B-cell immunodeficiency, and importantly, with an increased susceptibility to viral infections." (PMID 33459589, 2021). "However, recent studies have shown that CXCR3-biased cTfh cells or populations (based on PD-1 or ICOS expression) actually correlate with antibody responses and show helper function under viral infection or vaccination." (PMID 31300682, 2019). "After i.p. virus infection, the fraction of IFN-γ+ NK cells in the PEC was enhanced in both ICOS-KO and WT mice." (PMID 31283790, 2019). "Viral infection also increased the expression of granzyme B+ in the spleen and peritoneal exudate NK cells; but this response was lower in the NK PEC of ICOS-KO mice." (PMID 31283790, 2019). "In this study, using a mouse model of acute lymphocytic choriomeningitis virus (LCMV) viral infection, we demonstrate that mTOR complex 2 (mTORC2) kinase integrates TCR signaling and ICOS-mediated co-stimulation to promote late differentiation and functional maturation of virus-specific TFH cells." (PMID 29875775, 2018). "However, direct evidence for pro-infectious effect of ICOS and ICOSL in virus infection is missing." (PMID 30707726, 2019).
allergic asthma (7 papers, 2005 to 2024). A asthma with a basis in a pathological type I hypersensitivity reaction. "We found a lower frequency of CXCR5+ Tfh or Tfh1 subtypes and a higher frequency of CXCR5+ICOS+ Tfh, CXCR+ICOS+PD-1+ Tfh, Tfh2 or Tfh17 subtypes in children with allergic asthma." (PMID 38424520, 2024). "Emerging evidence has revealed an interaction between ILC2 and Treg cells in allergic asthma, which involves ICOS: ICOSL ligation." (PMID 36865540, 2023). "The CCR6+IL-17+ Treg cells subsets and the CCR6+ICOS+ Treg cells subsets decreased significantly in patients with allergic asthma compared with HC." (PMID 34497608, 2021). "We found the proportions of CCR6+IL-17+ and CCR6+ICOS+ Treg cells were both lower in patients with allergic asthma than in healthy subjects." (PMID 34497608, 2021). "It has been reported that activation of ICOS+ Tregs mediates allergic airway diseases, and targeting the ICOS/ICOS-L pathway may disrupt T follicular helper cell responses and ameliorate allergic asthma by disrupting the disease." (PMID 36077704, 2022). "TFH are crucial in the regulation of AAD and the ICOS/ICOS‐L pathway could represent a novel therapeutic target in allergic asthma." (PMID 30220084, 2019). "The finding that the MAPKs inhibitors very effectively inhibited several cytokines in CD4+ T cells costimulated through CD28 and ICOS, prompted us to investigate whether these selective MAPKs inhibitors may be active in an animal model of allergic asthma." (PMID 15833106, 2005). "CXCR5− Tph, CXCR5−ICOS+ Tph, CXCR5−ICOS+PD-1+ Tph, CXCR5+ICOS+ Tfh and CXCR5+ICOS+PD-1+ Tfh increased in children with allergic asthma." (PMID 38424520, 2024). "Similarly, we also found a lower frequency of CXCR5+ Tfh while a higher frequency of CXCR5+ICOS+ Tfh and CXCR+ICOS+PD-1+ Tfh in children with allergic asthma." (PMID 38424520, 2024). "Furthermore, suppression of IL-17 production by IL-35 producing ICOS+ Tregs and reversal of established IL-17-dependent AHR in mice is another example of ICOS involvement in controlling allergic asthma." (PMID 36865540, 2023).
colon cancer (7 papers, 2015 to 2025). "A significant down‐regulation of ICOS can be seen in colon cancer patients, especially in patients with either lymphatic or distant metastasis." (PMID 33949771, 2021). "ICOS-mediated helper activity for B cell responses, including GC B cell differentiation and subsequent exacerbation of lung pathogenicity in aged B6 mice, were generalized by similar findings in colon cancer–bearing aged BALB/c mice treated with anti–PD-1 therapy." (PMID 40198121, 2025). "The results showed that PDCD1LG2, ICOS, CD86, CD80, CD48, and CD274 showed a significant exclusion situation from RFX1 expression in colon cancer." (PMID 41425715, 2025).
hepatocellular carcinoma (7 papers, 2016 to 2024). A malignant tumor that arises from hepatocytes. "We selected inducible T cell costimulator (ICOS) rs4404254 T>C, rs10932029 T>C, CD28 rs3116496 T>C and CD80 rs7628626 C>A SNPs and assessed the potential relationship of these SNPs with hepatocellular carcinoma (HCC) risk." (PMID 31235485, 2019). "HepG2 cells were used in the current study with RNAi technology to knockdown the expression of the ICOS gene of co-stimulatory molecules in hepatoma cells, and to analyze the cell proliferation and invasion capacities of HepG2 cells after ICOS gene knockdown." (PMID 29316975, 2018). "An increased expression of ICOS-L by pDCs has been reported in hepatocellular carcinoma (HCC) and ovarian carcinoma, in which the presence of TA-pDCs and ICOS+ Tregs was predictive for disease progression." (PMID 39020402, 2024).
ovarian carcinoma (7 papers, 2013 to 2025). A malignant neoplasm originating from the surface ovarian epithelium. "High ICOS and LAG-3 levels were significantly associated with longer survival in the ovarian cancer TCGA cohort." (PMID 33747935, 2021). "Both ICOS and LAG-3 were found to be significantly associated with improved overall survival in The Cancer Genome Atlas (TCGA) ovarian cancer cohort." (PMID 33747935, 2021). "ICOS appears to be a particularly relevant immune gene in ovarian cancer, as ICOS and LAG-3 were the only genes determined from our multidimensional analysis that were validated independently in TCGA cohort." (PMID 33747935, 2021). "While the expansion and the suppressive function of these Foxp3+ICOS+Treg cells was strictly dependent on ICOS-ligand (ICOS-L) stimulation provided by tumor plasmacytoid dendritic cells (pDCs) in ovarian cancer and BC." (PMID 24124553, 2013). "Moreover, the researchers verified their results that indicated that higher CD8A expression in the high expression of ICOS was related to an improved survival rate among ovarian cancer patients." (PMID 36157232, 2022). "Additionally, both TApDCs and ICOS+ Foxp3+ Tregs predict disease progression in epithelial ovarian cancer patients." (PMID 34737750, 2021). "After incorporating the H-/L- expression groups of ICOS, TIGIT, CD8A, and TNFRSF8, the researchers categorized the ovarian cancer samples into 4 groups." (PMID 36157232, 2022). "By integrating the expression levels of ICOS, TIGIT, TNFRSF8, and CD8A, ovarian cancer patients can be divided into 4 subgroups, which have different prognosis." (PMID 36157232, 2022). "We also observed a strong correlation between ICOS and CTLA-4 in both our cohort (r = 0.8913, p < 0.0001) and the TCGA ovarian cancer cohort (r = 0.9093, p < 0.0001)." (PMID 33747935, 2021). "Finally, the expression levels of ICOS, TIGIT, TNFRSF8, and CD8A were integrated for the purpose of grouping ovarian cancer samples by prognosis." (PMID 36157232, 2022). "Indeed, Tregs infiltrating ovarian carcinoma express PD1 and also high levels of the inducible T-cell costimulator (ICOS)." (PMID 32025850, 2020).
systemic sclerosis (7 papers, 2020 to 2025). A chronic disorder, possibly autoimmune, marked by excessive production of collagen which results in hardening and thickening of body tissues. "Further, the levels of CXCR5+ICOS+PD-1+ Tfh cells are strongly associated with dermal fibrosis in patients with systemic sclerosis (SSc)." (PMID 32676074, 2020). "Elahee M and colleagues found that in systemic sclerosis patients, among PD-1highCXCR5- Tph cells, only the HLA-DR+ICOS- cells with cytotoxic properties are expanded and significantly correlated with the severity of interstitial lung disease." (PMID 40599793, 2025). "In addition, CXCR5+ICOS+PD-1+Tfh levels were associated with systemic sclerosis (SSc)." (PMID 40433386, 2025). "In patients with systemic sclerosis (SSc), skin fibrosis could be effectively controlled under the treatment with anti-IL-21 and anti-ICOS antibodies." (PMID 39469708, 2024). "Furthermore, systemic sclerosis patients’ dermal fibrosis is closely correlated with the presence of CXCR5 + ICOS + PD-1 + Tfh cells (SSc)." (PMID 36835428, 2023).
head and neck squamous cell carcinoma (6 papers, 2019 to 2024). A squamous cell carcinoma that arises from any of the following anatomic sites: lip and oral cavity, nasal cavity, paranasal sinuses, pharynx, larynx, and salivary glands. "Besides PD-L1, PD-L2, PD-1, CD80, CD86, CTLA-4, Tim-3, LAG3, and 4-1BB, we found the increase of an inducible co-stimulator (ICOS) expression in both HPV-positive head and neck squamous cell carcinoma and EBV-positive stomach adenocarcinoma tumors." (PMID 30911684, 2019). "A positive ICOS signature may indicate a better clinical outcome of anti-CTLA-4 immune therapy in HPV-positive head and neck squamous cell carcinoma and EBV-positive stomach adenocarcinoma patients." (PMID 30911684, 2019). "Moreover, ICOS may mediate the stimulation of antitumor immunity, and its expression is a survival predictor in head and neck squamous cell carcinoma." (PMID 39201462, 2024). "Chang SR’s findings in advanced head and neck squamous cell carcinoma (HNSCC) and oral squamous cell carcinoma (OSCC) indicate increased M2 macrophage expression and decreased ICOS expression." (PMID 39104717, 2024).
primary immunodeficiency (6 papers, 2018 to 2025). "In detail, symptomatic females showed a downregulation of eIF2, primary immunodeficiency, T-helper cell differentiation, and inducible T-cell costimulator (iCOS) signaling pathways." (PMID 37830598, 2023). "In summary, we present here novel information on cTFHs in patients with thymic pathology and primary immunodeficiency underlying DiGeorge syndrome and provide first data on the change in PD1 and ICOS expression on cTFHs and other T cell subsets during childhood." (PMID 30083170, 2018). "In enrichment analyses, DE genes specific to lymphoid tissues were found to be involved in several immunity-related canonical pathways: “Th1 and Th2 Activation Pathway”, “Primary Immunodeficiency Signaling”, “Th1 Pathway”, “iCOS-iCOSL Signaling in T Helper Cells”, and “T Cell Receptor Signaling”." (PMID 29899562, 2018). "B-, T-, and NK-cell development genes were broadly inhibited (CD3, lambda 5, ZAP70, ICOS, and the B-cell linker BLNK), as were genes involved in primary immunodeficiency signaling." (PMID 40036168, 2025). "Our work proposes new challenges for investigation in patients with primary immunodeficiency, which could lead to better understanding of the function of cTFHs, as well as temporal development of PD1 and ICOS expression." (PMID 30083170, 2018).
prostate carcinoma (6 papers, 2012 to 2025). A carcinoma that arises from epithelial cells of the prostate gland. "In prostate cancer, ICOS has been found on tumor-infilitrating lymphocytes including Tregs, and high expression induces an immunosuppressive environment." (PMID 40427227, 2025). "ICOS is an immune checkpoint protein that plays an important role in the tumor microenvironment of prostate cancer." (PMID 40427227, 2025). "However, anti-ICOS antagonist mAb also exhibited an anti-tumor effect in some malignancies, including follicular B-cell lymphoma and prostate cancer, which may account for the decrease in Treg function and proliferation." (PMID 36276141, 2022).
cervical cancer (5 papers, 2022 to 2025). A primary or metastatic malignant neoplasm involving the cervix. "This study constructed a cervical cancer prognosis model based on MPT‐driven necrosis‐related genes (ICOS, MMP3, POSTN) by integrating single‐cell and transcriptomic data." (PMID 40747615, 2025). "TISIDB was employed to examine immune infiltration in cervical cancer, revealing that IDO1 levels exhibit a significantly positive association with ICOS, C10orf54, CD27, CD28, CD70, and other immunostimulatory factors, which negatively regulate the expression of CD276." (PMID 39312339, 2024).